INS (insulin)
Diseases named in the same sentence as INS in open-access papers (continued):
Sharing a sentence is not in itself a finding about the gene and the disease.
Hypoglycemia (continued). "These latter patients were demonstrated to need a higher dose of insulin to attain optimal glycemic targets and to experience more frequent episodes of hypoglycemia." (PMID 30190702, 2018). "Intraportal insulin delivery via continuous intraperitoneal insulin infusion (CIPII) has demonstrated significant reductions in rates of severe hypoglycaemia when compared with CSII." (PMID 29423581, 2018). "Alongside this reduced GH content, and similar to our findings for blunted glucose-evoked insulin secretion in Nnat+/−p mice, pituitary GH secretion into the blood under hypoglycemia-stimulated conditions was severely reduced in these null animals." (PMID 30279096, 2018). "The independent variables were age, use of needle and syringe, planning of activities around the application of insulin, fear of hypoglycemia, and economic factors." (PMID 30116737, 2018). "We report data over 4‐week intervention periods and describe diurnal distribution of hypoglycaemia events and describe glucose excursion and insulin delivery before, during and after hypoglycaemic episodes." (PMID 29577536, 2018). "Advances in technology allowing improved insulin delivery and glucose monitoring can significantly reduce the burden of hypoglycaemia when used appropriately." (PMID 29423581, 2018). "The reduced amount of insulin resulted in more rapid recovery and higher 2‐hour post‐hypoglycaemia glucose levels during closed‐loop intervention." (PMID 29577536, 2018). "Participants would have liked advice from the system on suggestions for correction boluses, basal rates, insulin-carbohydrate ratios, and alerts to the risks of hypoglycemia." (PMID 29535079, 2018). "Renal failure affects hypoglycaemia development through decreased insulin clearance, diminished gluconeogenesis, and poor caloric intake." (PMID 29391050, 2018). "At the very least however, clinicians should be alert to the possibility of unrecognised hypoglycaemia in their older insulin-treated patients, and review them with this in mind." (PMID 28918198, 2018). "Case 4 sustained a hypoxic-ischemic brain injury following an insulin overdose; she was 3 years post-hypoglycemia." (PMID 30154755, 2018). "Fasting hypoglycemia and marked insulin sensitivity have sometimes been observed in GHD children due to diminished hepatic output through decreased gluconeogenesis or abnormal glucose mobilization." (PMID 29942285, 2018). "Continuous blood glucose–monitoring devices and computer-assisted closed loop systems for insulin delivery can prevent hypoglycemia and limit glucose level variability." (PMID 29300728, 2018). "We identified no patients among the 68 patients who were discharged taking only short-acting insulin who had return ED visits in the subsequent 48 h for hypoglycemia." (PMID 29799604, 2018). "In summary, IAS should be considered in cases of spontaneous hypoglycemia with a high insulin/C-peptide molar ratio." (PMID 30085133, 2018). "Careful monitoring of patients undergoing hypoglycemic drugs or insulin therapy and/or early specialist referral is thus advised to avoid hypoglycemia." (PMID 30571711, 2018). "It is estimated that 51% of people with T2DM recently commenced on insulin therapy (less than 3 years) experience at least one episode of symptomatic hypoglycaemia per year, while 7% experience at least one severe hypoglycaemia." (PMID 28803366, 2018). "Secondary endpoints included the change in laboratory-measured (clinic-collected) FPG and daily basal insulin doses and hypoglycemia occurring between the substudy BL and the end of the substudy." (PMID 29619381, 2018). "Vhlh mutant mice exhibit impaired glucose homeostasis including severe hypoglycemia and defective insulin and glucagon secretion." (PMID 30209343, 2018). "In this study, rodents were subjected to recurrent episodes of insulin-induced hypoglycaemia or saline control injections over a 4 week period." (PMID 29417183, 2018).
Hypoglycemia (continued). "The current study aims to assess hypoglycemia retrospectively and prospectively among insulin treated patients with T1DM or T2DM." (PMID 29433560, 2018). "After education on insulin dose titration and prevention for hypoglycemia and a 1-week acclimation period, subjects are randomized in a 1:1 ratio to either an ICT-based intervention group or a conventional intervention group." (PMID 28720103, 2017). "CHI-related hypoglycaemia features suppressed plasma ketones and free fatty acids but detectable plasma insulin, while glucagon stimulation characteristically increases blood glucose by greater than 30 mg/dL." (PMID 28566443, 2017). "Hypoglycemia, a complication of insulin or sulfonylurea therapy in diabetic patients, leads to brain damage." (PMID 28335557, 2017). "Data on the incidence of maternal hypoglycaemia will also be examined in the present study, and compared between different insulin treatments." (PMID 28100192, 2017). "The challenges of treatment include worsening hypoglycemia from insulin, as well as potential kidney and liver dysfunction from GSD-Ia, which limits medication use." (PMID 29127952, 2017). "Investigations in rodents additionally demonstrated that administration of exogenous serotonin increased insulin levels and blunted glucagon secretion in response to hypoglycemia." (PMID 28748177, 2017). "The insulin-induced hypoglycemia resulted in significant reduction in %GR of liquid only at the highest dose tested (1 U/kg) compared to the control group (C+V)." (PMID 28876363, 2017). "Studies have shown that severe acute insulin-induced hypoglycaemia results in oxidative stress in the rat brain, when neuroglycopenia cannot be evaded despite increased levels of cerebral glucose transporters." (PMID 28421113, 2017). "CGM with automated insulin infusion improved time in target and mean glucose in one trial and two trials showed a decrease in hypoglycemic episodes and time in hypoglycemia." (PMID 28098809, 2017). "Patients who experienced hypoglycemia had higher insulin doses prior to rewarming (16.2 versus 2.1 units/hr, p = 0.03)." (PMID 29075530, 2017). "Hypoglycemia mainly originates from an inadequate supply of glucose to compensate the reduction of blood glucose induced by the exogenous insulin." (PMID 28245289, 2017). "It was found that MT decreased AGEs through reduction of hypoglycemia indirectly via insulin-dependent mechanism directly." (PMID 28505155, 2017). "In this study, patients with hypoglycemia were older, suffered more severe renal dysfunction, had less endogenous insulin and more frequent use of sulfonylurea." (PMID 28067320, 2017). "Due to the different occurrence mechanism of hypoglycemia, the patients with insulinoma have suffered more serious hypoglycemia out of the unstifling secretion of endogenous insulin." (PMID 28293303, 2017). "Currently available tracers show a high and persistent renal uptake and low specific activity, resulting in side effects such as hypoglycaemia due to insulin secretion after activation of the GLP-1 receptor." (PMID 28103285, 2017). "Oral delivery of insulin is accompanied by different advantages like rapid hepatic insulinization, prevention of peripheral hyperinsulinemia, weight gain, hypoglycemia, and higher patient compliance." (PMID 30970818, 2017). "Larger studies using closed-loop insulin delivery during physical activity in free-living conditions and during competitive sports are warranted, as well as studies incorporating high-risk individuals who could especially benefit from the hypoglycaemia risk reduction." (PMID 28840263, 2017). "Blood samples obtained during hypoglycemia were insulin: 14 μIU/mL, ACTH; 19.6 pg/mL, and cortisol: 38.5 μg/dL." (PMID 28420223, 2017). "In order to avoid a too rapid decrease of blood glucose level throughout the course of the experiment, we induced hypoglycemia via repetitive administrations of insulin." (PMID 29077038, 2017).
Hypoglycemia (continued). "There is potential to treat hypoglycemia by endogenously inserting a glucose inducible promoter upstream of the insulin gene." (PMID 29340084, 2017). "Pancreas or pancreatic islet transplantation is a promising treatment for patients who lack endogenous insulin secretion, particularly those who experience recurrent episodes of severe hypoglycemia." (PMID 29073149, 2017). "The main side-effects of insulin—weight gain and hypoglycemia—have led to cautionary recommendations when used in patients with high risk of CV disease." (PMID 29270438, 2017). "Rates of hypoglycaemia in T2DM patients on insulin are lower than for T1DM patients, although disparity reduces with advancement of disease." (PMID 27896444, 2017). "Because of the heterogeneity, the diagnosis and differential diagnosis of hypoglycemia is very complicated, determined mainly on clinical features, insulin levels, onset time and several tests." (PMID 28293303, 2017). "(1985), a decrease in subcutaneous ATBF was found during hypoglycemia (~2 mmol/L), induced by insulin injected intravenously." (PMID 28174344, 2017). "The ‘stress’ in this test was to lower blood sugar (hypoglycemia) by injected insulin under very controlled conditions." (PMID 28365864, 2017). "Meanwhile, the relatively rapid GE induced by a marked hypoglycemia after high insulin dose is probably a result of the combination of two events: attenuation of the inhibitory pathways and simultaneous activation of muscarinic stimulatory receptors." (PMID 28876363, 2017). "Most infected animals showed evidence of an acute hypoglycemia, but also exhibited elevated levels of insulin, glucagon and GLP-1." (PMID 28085952, 2017). "In this study, IDet resulted in significantly lower fasting plasma glucose (FPG) in pregnancy compared with NPH insulin, with similar HbA1c levels and rates of hypoglycaemia." (PMID 28100192, 2017). "In patients on insulin therapy, inadequate caloric intake, exercise, renal insufficiency, and alcohol ingestion can precipitate hypoglycemia." (PMID 28913365, 2017). "One factor that has been postulated to precipitate hypoglycaemia is a high glycaemic index (GI) meal resulting in an increased glucose excursion followed by an exaggerated insulin response precipitating hypoglycaemia; the ‘over-swing phenomenon’." (PMID 28855269, 2017). "Laboratory evaluation showed elevated insulin with low cortisol and growth hormone levels at the time of hypoglycemia." (PMID 29075301, 2017). "Two studies of starvation-adapted humans have demonstrated full preservation of central nervous system function despite profound hypoglycemia induced by exogenous insulin administration." (PMID 30291062, 2017). "Increased self-administration of insulin has been performed to induce hypoglycemia and justify eating sweets and high carbohydrate meals." (PMID 28825608, 2017). "In concordance with these findings, in our study OR for hypoglycemia was increased in lean participants even after adjustment for insulin therapy, which points towards a more instable glucose metabolism in these patients." (PMID 28827839, 2017). "Although short-acting meglitinides are supposed to offer the advantage of having lower incidence of hypoglycemia, our results showed that the magnitude of the risk in advanced CKD patients was comparable to that of sulfonylurea or insulin." (PMID 29100450, 2017). "Intensive insulin therapy prevents CV complications but is constrained by hypoglycaemia and weight gain." (PMID 27935183, 2017). "A study conducted on MBD5 knockout mice revealed severe growth retardation and persistent hypoglycemia, hypoinsulinemia, enhanced glucose intolerance and elevated insulin sensitivity." (PMID 28604785, 2017). "PBH patients usually develop a postprandial high glucose level following carbohydrate-enriched food consumption stimulates GLP-1 and insulin release, with a rapid drop of glucose level and subsequent hypoglycemia." (PMID 28298900, 2017).
Hypoglycemia (continued). "Islet transplantation can completely resolve hypoglycemia and near-normalize glucose levels, achieving insulin independence for a limited period of time in up to 40% of patients." (PMID 28293906, 2017). "Despite high circulating levels of insulin and leptin in the present animal model of hypoglycaemia, the animals have increased food consumption, presumably driven mainly by the hypoglycaemia." (PMID 28421113, 2017). "The same authors reported a reduced GH peak (< 5 ng/ml) to insulin-induced hypoglycaemia test in 17% of subjects, 6% of patients having a GH peak equal to or less than 3 ng/ml." (PMID 28744309, 2017). "Instead, it is the BMI per se, and its interaction with the initial insulin dose, which accounts for the differences in hypoglycemia observed between the 2 treatment groups." (PMID 28151905, 2017). "Despite rapid advancements in insulin delivery and the on-going development of more physiological insulin preparations, achieving optimal glycaemic control while avoiding hypoglycaemia remains a challenge for many people with T1D." (PMID 28710224, 2017). "We showed that, compared with usual insulin pump therapy, day-and-night closed-loop insulin delivery significantly improved overall glycaemic control while reducing the burden of hypoglycaemia." (PMID 28094136, 2017). "The overnight hypoglycaemia event rate was comparably low with both closed-loop and open-loop insulin delivery devices in the present study, and the amount of time spent in hypoglycaemia below 3.3 mmol/l or below 3.9 mmol/l was very low." (PMID 28840263, 2017). "Overall, these studies suggest that P. falciparum secretes factors and activates the host immune system to increase pancreatic beta cell insulin secretion, which contributes to hypoglycemia." (PMID 29216326, 2017). "Repeated evaluations over ensuing months showed fasting hypoglycaemia with suppressed ketones, undetectable insulin and low but detectable C peptide levels." (PMID 28566443, 2017). "During the circadian period of food restriction, protection against hypoglycemia is accomplished by reduction of insulin secretion and activation of a catabolic program." (PMID 28884000, 2017). "Recurrent hypoglycemia can occur as a major complication of insulin replacement therapy, limiting the long-term health benefits of intense glycemic control in type 1 and advanced type 2 diabetic patients." (PMID 28234964, 2017). "The laboratory tests should ascertain glucose levels to allow for correction of insulin/anti-hypertensive drugs if the patient has been experiencing hypoglycaemia." (PMID 29061170, 2017). "The most common cause of hypoglycemia is intensive glycemic control, the involuntary intake of excessive doses of insulin or other glucose-decreasing drugs, or hypoglycemia unawareness." (PMID 28115020, 2017). "The main effect of GLP-1 is to enhance insulin secretion, but it ceases when blood glucose levels reach the normal range, thus avoiding hypoglycemia." (PMID 29152218, 2017). "Measuring serum insulin, proinsulin and C-peptide following prolonged fasting (72 h) during hypoglycemia is considered the gold standard for diagnosis of insulinoma." (PMID 28194228, 2017). "In contrast, effects of chronic (≥2 weeks) insulin-induced hypoglycaemia on cerebral glucose transporter levels or extent of oxidative damage to brain lipids have only been sparingly investigated." (PMID 28421113, 2017). "Therefore, the insulin action may have peaked during nighttime, which could have made those who injected insulin degludec in the evening or before bedtime more susceptible to nocturnal asymptomatic hypoglycemia." (PMID 28683068, 2017). "Both of the mutations in question give rise to congenital hyperinsulinism, characterized by dysregulated insulin secretion and hypoglycemia, and they were reported in two separate clinical studies." (PMID 28100260, 2017).
Hypoglycemia (continued). "Treatment was complicated by severe hypoglycemia with a blood glucose of 32 mg/dL, and she subsequently refused all forms of insulin." (PMID 29127952, 2017). "Insulin seems to increase BMD, but it can increase hypoglycemia-associated fall risk and it’s commonly used in the advanced phase of T2DM, increasing the fracture risk." (PMID 29021829, 2017). "A number of studies have shown that insulin degludec provides comparable glycemic control to insulin glargine, but is superior to insulin glargine in reducing the occurrence of nocturnal hypoglycemia." (PMID 28683068, 2017). "A higher dose of Dp alone (80 mg/kg) significantly reduced the effect of a marked hypoglycemia induced by 1 U/kg of insulin on GE while in combination with AT the effect was completely abolished." (PMID 28876363, 2017). "Our data indicates that special attention should be paid to prevention of hypoglycemia in elderly male patients when started on intensive insulin therapy with insulin pump." (PMID 28271075, 2017). "Congenital hyperinsulinism (CHI) is a rare genetic disorder characterized by excess insulin secretion, which results in hypoglycemia." (PMID 28600547, 2017). "These levels indicated that, with the same level of insulin sensitivity, participants with postprandial hypoglycemia had more insulin secretion both in the early and late stages compared to participants with NGT." (PMID 28913363, 2017). "The most accepted explanation for dumping hypoglycemia is the excessive insulin secretion secondary to a rapid absorption of simple carbohydrates with a large early peak of blood glucose." (PMID 28185153, 2017). "Participants were advised to manage glucose levels as normal throughout each experimental condition, and to record insulin dose, and treatment of hypoglycemia in the diary provided." (PMID 28684638, 2017). "Recurrent insulin-induced hypoglycemia blunts the counter-regulatory response (CRR) and the patient becomes unaware of the danger, a condition known as Hypoglycemia Associated Autonomic Failure or HAAF." (PMID 28234964, 2017). "The latest generation of CSII, the Medtronic 640G, can stop insulin delivery when it predicts hypoglycemia and has shown a reduction in hypoglycemia events." (PMID 28293906, 2017). "Some systems use insulin alone, but there are other systems in development that see both insulin and glucagon, more akin to a human pancreas, and theoretically better equipped to deal with problematic hypoglycemia." (PMID 28293906, 2017). "The results indicated that treatment with glyburide significantly increased the incidence of any neonatal hypoglycemia compared to treatment with insulin [RR, 1.89; 95%CI, 1.26 to 2.82; p = 0.002]." (PMID 28771572, 2017). "Second, this patient had suffered from recurrent hypoglycaemia since 19 months of age that required high glucose infusions; however, his insulin level was normal and an extensive endocrine workup was unremarkable." (PMID 29296277, 2017). "The health information includes level of blood glucose, insulin dose, details on hypoglycemia, food diary, and step count." (PMID 28720103, 2017). "The sympathetic-adrenal system is rapidly activated in order to increase blood glucose levels in hypoglycemia and the α2A-receptor is an important regulator of glycemia which, when activated, inhibits the release of insulin by pancreatic β cells." (PMID 28876363, 2017). "Recent evidence from clinical and laboratory studies has indicated that quinine is a potent stimulant to the release of insulin from the pancreatic beta cells and, in certain circumstances this can lead to hypoglycemia." (PMID 28836995, 2017). "Our glucose control algorithm has a very low incidence of insulin-induced hypoglycemia and prescribed very low insulin doses in the patients in the lowest glucose quintile." (PMID 28826408, 2017).